ENSG00000275664
Gene: Miscellaneous RNA gene on chromosome 21 (8,205,851 to 8,205,940, forward strand). Ensembl gene ENSG00000275664.
Gene Ontology:
Biological process: chromatin remodeling